U8 (U8 small nucleolar RNA )
Synonyms: LOC124900357
Gene: Small nucleolar RNA gene on chromosome 15 (30,384,959 to 30,385,091, reverse strand). Ensembl gene ENSG00000238519.
Gene Ontology:
Biological process: RNA processing
Cellular component: nucleolus
Homologues: Orthologues: chimpanzee U8 (98% identical), rabbit U8 (54% identical). Paralogues in human: U8 (100% identical), U8 (99% identical), U8 (98% identical), U8 (80% identical), U8 (78% identical), U8 (77% identical), U8 (76% identical), U8 (72% identical), U8 (71% identical), U8 (70% identical), U8 (69% identical), U8 (65% identical), and 1 more.